HMGB1 (high mobility group box 1)
Diseases named in the same sentence as HMGB1 in open-access papers (continued):
Sharing a sentence is not in itself a finding about the gene and the disease.
synovitis (9 papers, 2007 to 2025). Inflammation of a synovial membrane. "They demonstrated that HMGB-1 levels were higher in OA patients both in the synovium and synovial fluid and that synovial fluid HMGB-1 levels were positively associated with the degree of synovitis." (PMID 37047377, 2023). "HMGB1 is an endogenous pathogenic factor in synovitis, and the present results that oxaliplatin-induced nuclear HMGB1 sequestration coincided with beneficial therapy outcome support this notion." (PMID 18179697, 2008). "Extracellular HMGB1 plays a significant role in the development of synovitis, a common condition in KOA and hip OA, exacerbating joint degeneration." (PMID 40943691, 2025). "Elevated HMGB-1 in the synovial fluid relates to more severe synovitis, pain, and daily functional issues." (PMID 40943691, 2025). "Previous studies have reported that the SF level of HMGB1 is correlated with the severity of synovitis and pain in patients with knee OA, as well as a reduction in daily activities." (PMID 36906519, 2023). "In a synovitis cell model constructed using IL-1β, HMGB1, and LPS, intracellular IL-37 was responsively upregulated (more pronounced with stimulation of IL-1β)." (PMID 38053836, 2023). "In synovitis, hypoxic areas were found to be coincided with areas of maximal pathological HMGB1 expression, which substantiated the connection between ischemia and HMGB1 translocation." (PMID 28969092, 2017). "Nevertheless, the pro-inflammatory activity of HMGB1 in synoviocytes and its participation in synovitis during OA remain to be determined." (PMID 20799933, 2010). "Preventing extracellular HMGB1 release by intracellular sequestration provides a novel strategy to evaluate a functional role of HMGB1 in the pathogenesis of synovitis." (PMID 18179697, 2008). "A distinct TNF expression was observed in the lining layer as well as in sublining areas in synovitis, whereas HMGB1 and IL-1β expressions were most often restricted to the sublining areas." (PMID 17397533, 2007). "Moreover, the SF level of HMGB1 in patients with knee OA is positively correlated with the severity of synovitis and pain, as well as a reduction in daily activities." (PMID 36906519, 2023). "Synovitis specimens from both oxaliplatin treated and control animals showed massive cellular and extracellular HMGB1 expression, indicating that the nuclear entrapment of HMGB1 represented a reversible process." (PMID 18179697, 2008). "In the present study we asked whether nuclear sequestration of HMGB1 preventing HMGB1 release would be beneficial for synovitis treatment." (PMID 18179697, 2008). "Aberrant, extracellular HMGB1 expression has been demonstrated in human and experimental synovitis." (PMID 17397533, 2007). "The similarities between IL-1β and HMGB1 expressions in synovitis are noteworthy." (PMID 17397533, 2007).
ulcerative colitis (9 papers, 2020 to 2025). An inflammatory bowel disease involving the mucosal surface of the large intestine and rectum. "Although the sample size of this study was small, it provides clinical evidence supporting the role of NLRP3 and HMGB1 in ulcerative colitis and suggests their potential as novel diagnostic markers for the disease." (PMID 40688353, 2025). "In ulcerative colitis (a condition with chronic HMGB1 release), the DAMP HMGB1 was found to negatively regulate CPT1a (the rate-limiting enzyme for mitochondrial fatty acid oxidation, FAO) in macrophages." (PMID 41368629, 2025). "Bioinformatics analysis revealed high expression levels of several inflammation-associated genes, including TNF-α, HMGB1, and NLRP3, in the colonic tissues of patients with ulcerative colitis." (PMID 40688353, 2025). "A prospective observational study revealed elevated serum levels of NLRP3 and HMGB1 in patients with ulcerative colitis, which were positively correlated with disease severity." (PMID 40688353, 2025). "Fecal HMGB1 expression was significantly increased in pediatric and adult patients with Crohn’s disease and ulcerative colitis and correlated with disease severity fecal calprotectin and HMGB1 significantly correlated in pediatric and adult IBD patients." (PMID 37761298, 2023). "This study investigates whether increased HMGB1 levels are found in the intestinal mucosa of ulcerative colitis (UC) patients, and whether an anti-HMGB1 neutralizing-antibody (HnAb) can inhibit the intestinal inflammation elicited by dextran sulfate sodium (DSS) in mice." (PMID 33193406, 2020).
acute appendicitis (8 papers, 2011 to 2023). "HMGB1 could also serve as a diagnostic marker for severe blunt chest trauma and acute appendicitis and is associated with poor clinical outcomes in pediatric patients with acute traumatic coagulopathy (ATC)." (PMID 37520569, 2023). "The aim of this prospective study was therefore to evaluate the diagnostic value of preoperative serum High Mobility Group Box Protein-1 (HMGB-1) levels in patients with Acute Appendicitis (AA) who show normal white blood cell count (WBC) counts." (PMID 21507210, 2011). "The average HMGB-1 level of the 60 patients with Acute Appendicitis (AA) was 36.92 ± 15.43 ng/ml, while the average HMGB-1 value of the healthy group was 21.71 ± 11.36 ng/ml." (PMID 21507210, 2011). "There is a possible mechanism which is the increase of serum HMGB-1 levels in patients with acute appendicitis." (PMID 21507210, 2011). "release of HMGB1 from activated macrophages/monocytes may participate in tissue inflammation in acute appendicitis." (PMID 21507210, 2011). "For these reasons, serum levels of HMGB-1 rise during acute appendicitis." (PMID 21507210, 2011). "It has been demonstrated that novel inflammatory biomarkers, such as calprotectin, lactoferrin, high-mobility group protein B1 (HMGB1), and hepcidin, appear to be promising for the diagnosis of suspected appendicitis." (PMID 32953890, 2020). "In our study, we have also determined a correlation between an increase in HMGB-1 levels and WBC counts in acute appendicitis." (PMID 21507210, 2011). "The study demonstrates in a small pilot that there is a difference in expression of HMGB1 between those with and those without appendicitis." (PMID 21507211, 2011). "However, our study has also shown that in acute appendicitis, an increase in HMGB-1 levels may occur even when there is no increase in WBC numbers." (PMID 21507210, 2011).
acute coronary syndrome (8 papers, 2012 to 2025). Signs and symptoms related to acute ischemia of the myocardium secondary to coronary artery disease. "Indeed, the concentration-dependent activity of HMGB1 has been shown to be associated with the occurrence, development, and prognosis of various cardiovascular diseases by recent studies that include acute coronary syndrome, MI, and heart failure." (PMID 32286371, 2020). "In addition, HMGB1 may be biomarker that allows for the prediction of the risk of cardiovascular death in patients with acute coronary syndrome." (PMID 33114431, 2020). "Consistent with our results, previous studies utilizing Mon showed protective potential in acute coronary syndrome via down-regulating HMGB1 production in platelets." (PMID 37498374, 2024). "It is noteworthy that patients with acute coronary syndromes or stroke were found to have significantly higher serum levels of immunoreactive HMGB1 than healthy controls." (PMID 27713681, 2016). "Both of these studies demonstrate that HMGB1 levels can be used as a new prognostic biomarker in patients with acute coronary syndrome." (PMID 24363498, 2013). "In addition, experimental models of acute coronary syndromes and cerebrovascular accidents showed that HMGB1 is involved in the amplification of the inflammatory response that occurs during acute ischemic injury as well as in the recovery and remodeling that occurs after ischemia." (PMID 27713681, 2016).
alcoholism (8 papers, 2007 to 2026). "Particularly, RAGE activation by HMGB1 was described to cause cell death through NF-κB pathways in alcohol brain damage and AD." (PMID 38535924, 2024). "Our findings suggest that recurrent TLR7 activation by ethanol-induced microglial let-7 and HMGB1 release contributes to the progressive neurodegeneration associated with alcoholism." (PMID 28118842, 2017). "Adolescent LPS (1.0 mg/kg, i.p.)treatment, which mimics AIE-induced HMGB1-mediated neuroinflammation, induces adult alcohol tolerance and blunts HMGB1 release across cumulative ethanol doses on the ERB." (PMID 41780544, 2026). "The release of HMGB1 by ethanol and/or other factors provides new therapeutic targets for brain protection against neuroimmune induced degeneration and alcoholism." (PMID 24551070, 2014). "The present study aimed to investigate whether endotoxin lipopolysaccharides (LPS) and high-mobility group box-1 protein (HMGB1), a key inflammatory mediator, as well as the metabolic fat mass hormone leptin, are reliable biomarkers for the estimation of alcohol dependence and abstinence." (PMID 42198566, 2026). "The first-step variables introduced in the model were HMGB1, sRAGE, ROS/RNS, ApoD, NRF2, age of alcohol use onset, age of alcohol dependence onset, duration of alcohol use, duration of alcohol abstinence, and periods of alcohol abstinence." (PMID 38535924, 2024). "Using a backward stepwise method (Wald test) of the model, the predicted covariables were restricted to HMGB1, sRAGE, ROS/RNS, age of alcohol dependence onset, and periods of alcohol abstinence." (PMID 38535924, 2024). "On the topic of alcoholism, as with the biomarkers discussed above (OPN and HMGB1), we also chose two studies with the largest study groups." (PMID 37298365, 2023). "Although the mechanisms underlying ethanol-induced innate immune gene induction in the brain are complex involving many neuroimmune genes, HMGB1, TLR, and other neuronal–glial neuroimmune signaling molecules contribute to the neurobiology of alcoholism." (PMID 25787746, 2016). "The two prioritized candidate gene lists (87 genes for FAS and 65 for alcoholism) had only two high priority candidate genes in common – GNAS complex locus (GNAS) and high mobility group protein B1 (HMGB1)." (PMID 17961254, 2007). "Thus, the neuropathology of human alcoholism involves increased expression of TLR7, HMGB1, and microglial CD11b." (PMID 28118842, 2017).
aneurysm (8 papers, 2016 to 2026). Bulging or ballooning in an area of an artery secondary to arterial wall weakening. "A significant attenuation of pro-inflammatory cytokines, including IL-1β and HMGB1, associated with aneurysm formation were seen in the SPL-treated mice compared to saline-treated mice." (PMID 36776267, 2023). "A significant attenuation of inflammatory cytokines, including IL-1β and HMGB1, associated with aneurysm formation was seen in the PBN-treated mice compared with Ang II alone." (PMID 35315432, 2022). "Compared to the sham/SD rats, the expression levels of RAGE, MR, and HMGB1 in the rats with unruptured and ruptured aneurysms were significantly increased in the brain parenchyma adjacent to the Lt PCA with unruptured and ruptured IAs, but not in other areas." (PMID 35725479, 2022). "Importantly, the downregulation of angiogenic and matrix-degrading genes such as VEGF, MMP-2, MMP-9, HMGB1, and NF-κB p65 further supports its role in mitigating ECM destabilization and inflammatory amplification—hallmark events in aneurysm pathogenesis." (PMID 40868841, 2025). "Studies have shown that HMGB1 and S100A12, another recently recognized TLR4 ligand, contribute to vascular inflammation and MMP production, implicating a role of TLR4 in aneurysm lesions." (PMID 26741694, 2016). "Elevated HMGB2 and HMGB1 levels were associated with higher risks of AAA (HMGB2: OR: 1.158, 95% CI: 1.011–1.325; p < 0.05; HMGB1: OR: 1.275, 95% CI: 1.048–1.551; p < 0.05) and aneurysm rupture (HMGB2: OR: 1.117, 95% CI: 1.005–1.241; p < 0.05; HMGB1: OR: 1.212, 95% CI: 1.003–1.465; p < 0.05)." (PMID 40776964, 2025). "Moreover, Ang II-induced overexpression of critical genes involved in aneurysm pathogenesis—such as VEGF, MMP-2, MMP-9, HMGB1, and NF-κB p65—was significantly downregulated following CL treatment." (PMID 40868841, 2025). "In summary, although the TNF-α level and macrophage number were similar in ScSnJ and ScNJ mice during aneurysm initiation, knockout of TLR4 signaling reduced IL-6 and MCP-1 levels, suppressed HMGB1 and RAGE expression and interfered with consequent accumulation of macrophages." (PMID 26741694, 2016). "Interestingly, high mobility group box 1 (Hmgb1), a ligand for Havcr2 in splenocytes and dendritic cells, was increased in groups that failed to develop aneurysms but decreased in AAA mice regardless of sex and female human patients." (PMID 41216502, 2026).
atrial fibrillation (8 papers, 2015 to 2025). A disorder characterized by an electrocardiographic finding of a supraventricular arrhythmia characterized by the replacement of consistent P waves by rapid oscillations or fibrillatory waves that vary in size, shape and timing and are accompanied by an irregular ventricular response. "The nonsystematic review confirms the pivotal role of molecules such as S100 proteins, high-mobility group box-1, and heat shock proteins in the molecular pattern of atrial fibrillation." (PMID 36555588, 2022). "In our literature review, we evaluate the role of HMGB1 proteins, heat shock proteins, and S100 in the pathophysiology of atrial fibrillation, offering suggestions for possible new therapeutic strategies." (PMID 36555588, 2022).
autism (8 papers, 2017 to 2025). Persistent deficits in social interaction and communication and interaction as well as a markedly restricted repertoire of activity and interest as well as repetitive patterns of behavior. "HMGB1 serum concentrations have been found to positively correlate with deficits in social interaction as assessed with the Autism Diagnostic Interview-Revised (ADI-R) in young adults with ASD." (PMID 34198762, 2021). "An independent direct association has been found between HMGB1 blood levels and the domain A scores in the autism diagnostic interview-revised (ADI-R), which reflects social deficits." (PMID 29682486, 2017). "Additionally, HMGB1 SCs were found to positively correlate with deficits in social interaction as assessed with the Autism Diagnostic Interview-Revised (ADI-R)." (PMID 34198762, 2021). "The association of HMGB1 with autism was demonstrated being severity-related." (PMID 30577568, 2018). "In rodent models of autism, HMGB1 exacerbates vascular permeability and leukocyte infiltration via the HMGB1/RAGE/TLR4 axis, leading to persistent neuroinflammation." (PMID 40557138, 2025). "Research has also been carried out on the topic of autism and changes in HMGB1 protein levels, through which some authors are attempting to explain the pathogenesis of autism." (PMID 37298365, 2023). "Children with autism showed significantly higher serum HMGB1 levels compared with typically developing control children, and these findings suggest that inflammatory processes mediated by HMGB1 may be associated with the specific cognitive characteristics observed in autistic individuals." (PMID 37298365, 2023). "In recent years, reviews have been published on the role of HMGB1 as an important biomarker in nervous system diseases, as well as in paediatrics, wherein authors have discussed the possible mechanisms by which HMGB1 mediates autism." (PMID 37298365, 2023). "At the same time, the serum HMGB1 level is positively correlated with the severity of autism, and the higher the HMGB1 level, the worse the social interaction ability." (PMID 36388178, 2022). "In fact, treatment with inhibitors of HMGB1 activity was found being able to reduce the inflammatory response in a wide range of preclinical autism models." (PMID 30577568, 2018). "gov/ pubmed) to identify all original articles published in English, on the basis of the following keywords: “HMGB1”, “autism”, “autism spectrum disorder”, “neuroinflammation”, and “child”." (PMID 29682486, 2017). "A systematic search has been carried out through Medline via Pubmed to identify all original articles published in English, on the basis of the following keywords: “HMGB1”, “autism”, “autism spectrum disorder”, “neuroinflammation”, and “child”." (PMID 29682486, 2017). "Interestingly, in children with autism, faecal HMGB1 levels correlated with the severity of gastrointestinal symptoms." (PMID 37298365, 2023). "In addition, studies in which adults with autism were the study group show that autistic disorders can be influenced by serum levels of HMGB1." (PMID 37298365, 2023). "However, there are few clinical and preclinical studies on autism at present, and more research is needed to clarify the role of HMGB1 in the pathophysiology of autism and to clarify the specific molecular mechanism by which HMGB1 is involved in autism." (PMID 36388178, 2022). "We aimed to assess HMGB1 serum concentrations (SCs) in high-functioning ASD children compared to typically developing (TD) controls and to explore their associations with the autism spectrum quotient (AQ), the empathy quotient (EQ), and the systemizing quotient (SQ)." (PMID 34198762, 2021).
bone cancer (8 papers, 2012 to 2025). A primary or metastatic malignant neoplasm affecting the bone or articular cartilage. "Two studies focused on HMGB1, finding that spinal HMGB1 upregulation contributes to bone cancer pain and that treatment with anti-HMGB1 significantly reversed bone cancer-induced mechanical allodynia." (PMID 38940936, 2024). "Blocking HMGB1 with anti-HMGB1 monoclonal antibodies ameliorates pain behaviors in rodent models of neuropathic and bone cancer pain while injection of recombinant HMGB1 elicits pain behaviors in rodents." (PMID 27010488, 2016). "More importantly, multiple exposures to HMGB1 neutralizing antibodies partially reverse spinal nerve ligation-induced mechanical hyperalgesia and bone cancer pain." (PMID 22824385, 2012). "HMGB1 expression increases in rats that suffer from bone cancer pain." (PMID 25120576, 2014). "Thus, the blockade of spinal HMGB1 could attenuate bone cancer pain and downregulate the expression of IL-1β in a dose-dependent manner." (PMID 34638667, 2021). "In bone cancer pain (BCP) models, tumor-mediated bone destruction produces lactate, PGE2, extracellular ATP, and high-mobility group box 1 (HMGB1)." (PMID 40579593, 2025).